CD86 (CD86 molecule)
Diseases named in the same sentence as CD86 in open-access papers (continued):
Sharing a sentence is not in itself a finding about the gene and the disease.
tumor (continued). "Apoptosis of tumor cells, the ratio of CD8+/CD4+ in CD3+ cells, CD80+CD86 in DD11c+ cells, and IFN-γ+ in CD3+ all were significantly higher than challenge with IL-2 or the microorganism alone." (PMID 38585738, 2024). "After the euthanasia of murine subjects, an assessment of oncolytic efficacy was performed through flow cytometry analysis of murine blood and tumor tissue, targeting CD83, CD86, CD8, and CD4." (PMID 39062070, 2024). "Then the levels of CD86 and CD206 in tumour tissues in three groups were measured with immunohistochemical staining." (PMID 39500733, 2024). "Metformin combined with a tumor vaccine significantly increased the expression of M1 markers CD86 and MHC-II in TME, reduced tumor growth and inhibited lung metastasis in select tumor models." (PMID 38659591, 2024). "Selective blockade of the CD28 ligand CD86 inhibited the Treg response and promoted CTL priming and tumor control." (PMID 38349740, 2024). "In the TC-1 tumor model, the frequency of cDC1s and cDC2s coexpressing CD80 and PD-L1 was significantly increased when RT was combined with CD86 blockade." (PMID 38349740, 2024). "Western blot results further demonstrated that the protein expression of M1 and M2 macrophage markers CD86 and CD163 in tumor tissues was significantly higher than in paracancerous tissues (p<0.05)." (PMID 39531417, 2024). "CKO diminished the population of CD45+CD11c+F4/80+CD206+CD86− M2 macrophages, while it increased CD45+CD11c+F4/80+CD206−CD86+ M1 macrophages and CD45+CD3+CD4−CD8+ cytotoxic T cells infiltrating the tumor." (PMID 38297161, 2024). "The expression of the immune checkpoint molecules CD86 and PD-L1 and particularly the reduced expression of CD80 in groups 3 and 4 indicate an influence of the investigated immune checkpoints on tumor regression." (PMID 38962703, 2024). "Our results showed the highest percentage of mature DCs in the combination treatment group along with increased CD86, CD80, and MHC-II in tumor-infiltrating DCs compared with the control." (PMID 39772073, 2024). "After JHU083 treatment, the in vivo TAMs were more phagocytic of tumor cells, and, importantly, this increased phagocytosis was observed in both CD206+ M2 TAMs and CD86+MHCII+ M1 TAMs." (PMID 38701369, 2024). "Tissue microarrays of the invasive front as well as the tumor core of BCC and cSCC samples were used to evaluate PD-1, PD-L1, CD28, and CD86 expression and their topographic distribution profiles by chromogenic immunohistochemistry." (PMID 39329753, 2024). "Our findings highlight the precise binding specificity of AYA22T-R2-13 for CTLA4-B7-1/B7-2 (CD80/CD86) or CD94/NKG2A-HLA-E interactions, positioning it as a valuable tool for immune checkpoint blockade aptamer research in murine tumor models." (PMID 38473398, 2024). "Multiplex immunofluorescence for CD86 and CD163 was performed to directly show the infiltration of macrophages in tumor tissues of 615-line mice." (PMID 38238529, 2024). "In the A2-APM treated tumor cell group, CD206, the marker of inhibition, significantly decreased, and CD86, the marker of anti-tumor, increased." (PMID 38320994, 2024). "Immunogenic cell death, maturation and activation of DCs (CD11c+, CD11c+CD86+, CD11c+MHC-I+), cytotoxic T-lymphocyte anti-tumor immune effects (CD3+, CD3+CD4+ and CD3+CD8+), increased stimulating the transition of T cells to Th1 phenotype." (PMID 38791452, 2024). "Based on above three diagnostic markers, we developed a diagnostic nomogram for TNBC patients, which showed that patients with high expressions of CD86, TNFRSF17, and TNFRSF1B had a high probability of “hot” tumor." (PMID 39007147, 2024). "The tumor tissues were immunohistochemically stained with CD4-, CD8-, CD11c-, CD86- and GFP-specific Ab to assess immune cells infiltration." (PMID 38835775, 2024). "DCs are highly efficient APCs that activate antitumor CD8+ T cells by phagocytosing dying tumor cells and presenting co-stimulatory molecules, such as CD80 and CD86." (PMID 38994018, 2024).
tumor (continued). "(B) Representative flow cytometry measurements of macrophage polarization: MHCII and CD86 for M1-like (anti-tumor) markers, and CD163 and CD206 for M2-like (pro-tumor) markers." (PMID 38805560, 2024). "In summary, all antibodies except CD86 showed significantly higher levels in cSCC as compared to BCC for both the invasive front and the tumor core." (PMID 39329753, 2024). "M1 polarized macrophages mainly play a pro-inflammatory role in killing tumor cells by highly expressing CD80 and CD86 molecule while secreting elevated levels of IL-1β and TNF-α proinflammatory cytokines." (PMID 38430256, 2024). "Initially, we probed the expression levels of CD86 and CD80 essential molecules for CTLA-4 interaction on tumor cells." (PMID 38473398, 2024). "The literature reports also demonstrate that TBX3 upregulates important gene targets involved in tumor development, angiogenesis and ion transport such as versican (VCAN), CD9, chromo-domain helicase DNA binding protein 1 (CHDR1) and CD86." (PMID 39358558, 2024). "Compared to naïve DCs, DCs challenged with tumor supernatant exhibited significantly suppressed expression of MHC II, CD40, CD80, and CD86." (PMID 38164187, 2024). "AIP-mutation positive pituitary tumors were associated with an altered tumor microenvironment including increased CD86+ macrophage and FOXP3+ Tregs infiltration, and upregulation of tumor-derived cytokine CCL5 (also known as RANTES)." (PMID 38479600, 2024). "To test if these co-stimulatory molecules played a role in local and abscopal tumor control in hRT/lena-treated mice, we blocked CD70, CD83, and CD86 during hRT/lena treatment by co-administration of blocking antibodies." (PMID 38646638, 2024). "There are only very few studies on cell lines and tumour cells using CTLA-4 receptor ligands, including CD80 and CD86." (PMID 39286684, 2024). "At the same time, the reduction in tumor Treg prevents the downregulation of costimulatory B7-family proteins (CD80 and CD86) on cDC in a CTLA-4-dependent manner." (PMID 39470607, 2024). "It has been demonstrated that the low presence of CD86 M1 TAMs and the high presence of CD206 M2 TAMs correlate significantly with an aggressive tumor phenotype and a poorer prognosis." (PMID 38611749, 2024). "DCs exposed to A. vulgaris extract, begin to express significantly more MHC II, costimulatory CD86 molecules systemically and express more CD40 ligand locally, thus becoming competent to correctly display tumor antigens and activate the T cell response." (PMID 38920557, 2024). "Initially TNF-γ works by recruiting cohorts (CXCL9, CXCL10, CXCL11, and CXCR3) to promote antigen presentation (MHC class I and class II), T-cell initiation and activation (CD80, CD86, and CD40), and tumor cell killing (Fas and FASL)." (PMID 39835116, 2024). "The percentage of mature DCs, characterized by dual‐positive CD86 and CD80 signals, increased from 23.4 to 75.3% in the CD11c+ cell subset of the tumor." (PMID 38774917, 2024). "Ultimately, the recombinant CD86‐P2A‐EGR3 mRNA vaccine was developed to enhance anti‐tumor immune responses, thereby increasing survival and tumor control." (PMID 38973154, 2024). "In the mouse tumor model, the levels of the macrophage co-stimulators CD80 and CD86 were higher in tumors of the combination group than in the Mn2+ and IL-12 alone groups." (PMID 38175694, 2024). "In the stimulatory status, CD86 can up-regulate its expression via antigen-presenting cells (APCs), and further combine with CD28 delivering stimulation signals to promote anti-tumor immune and enhance activating T cells." (PMID 39007147, 2024). "Therefore, the number of patients in this study is limited to 42, and evaluation of CD86-low status as a predictive biomarker requires a follow-up validation study, with a planned number of patients determined using the Reporting Recommendations for Tumor Marker Prognostic Studies guidelines." (PMID 39302712, 2024).
tumor (continued). "The results showed that CD200, CD80 and TNFRSF14 were the highest in tumor tissues, CD274 (PDL1), CD86, LGALS9, NECTIN2, PDL2, PVR were lower than those in adjacent tissues but higher than those in normal tissues, and FGL1 was the lowest in tumor tissues." (PMID 39120585, 2024). "In lymphocyte-depleted cancer, PD-1 and CTLA-4 blockade promote radiotherapy-induced Treg responses in a CD86-dependent manner and prevent CD8+ T-cell mediated tumor control." (PMID 38349740, 2024). "CTLA-4 is upregulated in tumor-specific T cells and acts as an “off” switch when it binds CD80 (B7-1) or CD86 (B7-2) on the surface of cancer cells." (PMID 38893211, 2024). "The expression of two TAM markers in our studies revealed that macrophage scavenger receptor 1 (MSR1/CD204) and CD86 were expressed at very low levels in normal tissue (less than 0 log2 TPM; <1 TPM) and exhibited increased levels in tumor tissue." (PMID 38539537, 2024). "The surface expression of activation markers, including CD80, CD86, and MHC-I on tumor-infiltrating DCs, was markedly increased in TMPyP4-treated MC38 tumors." (PMID 39528472, 2024). "Accordingly, the presence of VM can affect the infiltration of immune cells into the tumour through the upregulation of immune checkpoints, such as CD28, CD86, BLTA, and CD40LG, which can inhibit the immune response." (PMID 39718433, 2024). "IL-18 signaling promotes the activation and expansion of NK cells and improves their cytotoxicity and tumor activity, as well as the CD80, CD86, and HLA-DR expression in APCs." (PMID 39599846, 2024). "We assessed the expression of activation markers CD40 and CD86 in TdLNs and tumors from hsBCL9z96-treated CT26 tumor-bearing mice by flow cytometry." (PMID 38811552, 2024). "The flow cytometry analysis of the blood and tumor of mice with induced tumor treated with combined treatment revealed elevated levels of CD83, CD86, CD8, and CD4 (76.3, 66.9, 83.7, and 14.4%, respectively)." (PMID 39062070, 2024). "Immune analyses at the endpoint showed that ZCVCT26@D‐Gel, with its capability to induce pseudo‐oncolysis in tumor cells upon bioorthogonal anchoring, resulted in higher frequencies of CD80+CD86+CD11c+ mature DCs in tumor‐draining lymph nodes (TDLNs)." (PMID 38279587, 2024). "Tumor‐secreted factors potentiated an M2‐like phenotype with a higher resultant CD206 in WT macrophages compared to KO macrophages, however, CD86 expression was similar in WT and KO macrophages." (PMID 38308188, 2024). "ICIs, by blocking the PD1-PD-L1 and the CD86/CTLA4 axes, prevent tumor cells from releasing wrong messages to T cells, thereby restoring tumor-induced immuno-deficiency in TIME." (PMID 39007147, 2024). "Subsequently, TAMs were isolated from both adjacent normal and tumor tissues and analyzed by flow cytometry, which revealed a marked difference in subtype distribution, with elevated levels of CD206 and decreased CD86 in tumors." (PMID 38342611, 2024). "To characterize the cytolytic effect of the CAR/CCR T cell construct on CD19-expressing tumor cells with different expression levels of both CD80 and CD86 we prepared a range of in vitro co-culture experiments." (PMID 38340727, 2024). "M1 macrophages are tumor-resistant and can be identified by different phenotypic markers, including CD80/B7-1, CD86/B7-2, HLA-DR, and NOS2." (PMID 39599846, 2024). "RMC-4998 treatment also increased the presence of CD86+MHCII+ and PD-L1+ interstitial MΦs with the RMC-4550 treated tumours having a distinct increased proportion of these subsets." (PMID 39322643, 2024). "IFN-γ has the potential to exert its anti-tumor effects by acting directly on malignant cells, as well as other cells in the TME, including endothelial cells and immune cells, such as CD86 positive M0-derived M1-like macrophages." (PMID 38255296, 2024).
tumor (continued). "Tumor-draining lymph nodes (TDLNs) of MC38 tumor-bearing C57BL/6 mice treated with PBS, OX+GA, OX-NCP, GA-NCP, or OX/GA were collected and analyzed for MHCII+CD86+ expressions in DCs (CD45+CD11b+CD11c+) 4 days after treatment." (PMID 39018400, 2024). "As expected, DOX@3D-MPs treatment remarkably increased the amounts of CD11c+CD80+CD86+ and CD11c+MHC-II+ cells in tumor tissues, revealing that DOX@3D-MPs efficiently promoted intratumor DC maturation." (PMID 37875473, 2023). "The expression level of gene sets related to cytotoxic T cell activation (perforin, granzyme A, and granzyme B), costimulation (CD80 and CD86), and immune checkpoints (LAG3, CTLA4, PD-L1, and PD-1) was found to be increased in the tumor tissue." (PMID 37606040, 2023). "Specifically, we observed direct changes in the tumor microenvironment after using a ferroptosis inducer in this tumor subtype with the recruitment of CD3e+, CD4+, CD8+, and CD86+ cells, and a reduced number of CD206+ cells." (PMID 36861444, 2023). "In this study, the bioinformation analysis first found that PD-L1, CD86, and CD206 were differentially expressed in HCC and correlated with the immune infiltration of tumor cells." (PMID 37306737, 2023). "Mice receiving adjuvant NIPP treatment after surgical resection of orthotopic breast cancer tumors showed an increased percentage of mature CD86+ and CD80+ DCs in tumor-draining lymph nodes, and increased numbers of tumor-infiltrating CD4+ and CD8+ T cells." (PMID 36831415, 2023). "The correlation between the expression of PD-L1, CD86, and CD206 and the infiltration of immune cells was analyzed using the Tumor Immune Estimation Resource (TIMER)." (PMID 37306737, 2023). "For this purpose, we generated T2 tumor cells with a double KO of both CD28 ligands CD80 and CD86 (termed “T2 KO”)." (PMID 36732507, 2023). "Herein, bioinformatics analysis found that the expression levels of PD-L1, CD86, and CD206 were downregulated in tumor tissues, while immunohistochemical staining data showed that PD-L1, CD86, and CD206 were overexpressed in tumor tissues." (PMID 37306737, 2023). "MHCI (H2KB and H2DB), MHCII, CD80, CD86 and PD-L1 expression on the AT3OVA tumours were all significantly increased in response to combined inhibitor treatment compared with vehicle controls." (PMID 37582853, 2023). "In pancreatic ductal adenocarcinoma (PDAC), TMAO resulted in increased expression of co‐stimulatory markers such as MHCI, MHCII and CD86 in TAM and reformulated the tumour environment to an immune‐activated state to inhibit tumour growth." (PMID 38082435, 2023). "CD86 appears to participate in immune invasion in AML and is an important player in the tumor microenvironment in this malignancy." (PMID 37064861, 2023). "Consistent with the in vitro results, MC38‐tumor‐infiltrating cDC1 also showed upregulated CD40, CD80, CD86, and MHC‐II expression after RA treatment." (PMID 36876644, 2023). "XCR1+ cDC1s play a key role in cross-presenting tumor antigens on MHC I to activate antitumoral cytotoxic T cells, and mature LAMP3-high DCs in our dataset had the highest expression of CD80/CD86 costimulatory signals needed to fully activate T cell responses." (PMID 37433281, 2023). "For instance, the endocytosis of melanoma-derived microparticles efficiently promoted the formation of MHC class I-tumour antigen complex together with the induction of the costimulatory molecules CD80 and CD86." (PMID 39698297, 2023). "We found that β2AR signaling limits DCs function in the presence of tumor antigens by decreasing the expression of MHC-II, CD86, and CD40." (PMID 37006295, 2023). "RA‐treated B16‐OVA tumor cells markedly increased the surface expression of activation markers, including CD40, CD80, CD86, MHC‐I, and MHC‐II on BMDCs." (PMID 36876644, 2023). "The gene expression omnibus (GEO) and the Cancer Genome Atlas (TCGA) database were used to analyze the expression of PD-L1, CD86, and CD206 in different tumor tissues." (PMID 37306737, 2023).
tumor (continued). "We developed two tripartite classification systems of CD86+ and CD206+ macrophages, namely, ratio and quantity subgroups, as prognostic tools for tumor recurrence and mortality." (PMID 37342343, 2023). "In the tumor center and in the tumor periphery, the CD68+CD86+MRP8-14neg M1, CD68+CD163+ CD206neg M2, and CD68+CD206+CD163neg M2 macrophage subtypes were far from the MCs." (PMID 37637998, 2023). "In contrast, co-culturing untreated tumor cells with the hmDCs even significantly decreased the expression of CD83 for the cell line HSC-4 and UM-Scc-47 as well as the activation marker CD86 for all cell lines, but the HPV-positive cell line UD-Scc-2." (PMID 37857049, 2023). "Supernatants from irradiated tumor cells induced elevated expression of CD80 and CD86 on the surface of DCs and a 4-fold increase in infiltration of CD11b+CD11c+MHC-II+ DCs." (PMID 37833255, 2023). "The maturity of DC/tumor fusion cells is usually determined by costimulatory molecules (e.g. CD80, CD86, as well as NHC-II) expression levels." (PMID 37419930, 2023). "As expected, CD68, CD86, CD206, and Arg-1 levels were more significant in tumor tissues than in ANT." (PMID 38264642, 2023). "The dying tumor cells would release TAAs and T-cell stimulating factors (CRT, CD80, CD86), activating antitumor immune response." (PMID 36759928, 2023). "While PD-L1 was similarly upregulated, the AT3 tumours were still able to engage immune evasive strategies by downregulating CD80 and CD86 molecules." (PMID 37582853, 2023). "We also found that the mRNAs of CD86 and BTNL8 were expressed in the siGPX4 group, suggesting that knocking down GPX4 increased T-cell activity and killed tumor cells." (PMID 37649598, 2023). "In constant, M2 macrophages express the surface markers of CD163, CD86, and CD206 (MRC1, mannose receptor C-type 1), secrete cytokines including IL-10, TGF-β, and IL-6, and function in wound repair and tumor growth." (PMID 37749600, 2023). "CD19, CD20, CD38, CD86 and CD138 detected in tumour tissues were used as markers for positive prognosis." (PMID 36890557, 2023). "Exposure of DCs to the 33% Cu-doped TiO2 NPs resulted in higher levels of MHCII, as was also observed for DCs in the tumor-draining lymph nodes, insignificantly affected activation markers CD80 or CD86." (PMID 36915084, 2023). "Flow cytometry analysis confirmed the upregulation of antigen-presenting markers CD86 and MHC-I molecules in tumor-infiltrating DCs of the LR-DPVB-treated group compared to the DPVB-treated group, indicating enhanced maturation and antigen-presenting function." (PMID 38001101, 2023). "It was shown that stimulation with tumor‐conditioned medium (TCM) prepared from glioma cells inhibited the induction of DC maturation by suppressing the expression of CD80, CD86, and IL‐12 p70, and promoting IL‐10 expression." (PMID 37088950, 2023). "The value of PD-L1, CD86, and CD206 expression in tumor tissues should be prospectively verified in multicenter studies." (PMID 37306737, 2023). "The phenotype of M1 macrophages is CD86, while that of M2 macrophages is CD206, producing two opposite effects of anti-tumor or promoting tumor development through mutual transformation." (PMID 37306737, 2023). "Tumour-infiltrating DCs process and present tumour antigens and gradually differentiate into mature DCs that express co-stimulatory molecules CD80 or CD86 to interact with T cells to resist tumours." (PMID 36463323, 2023). "The cell suspension was prepared to analyze the populations of CD86+CD80+ and CD8+CD45+ cells in tumor tissues." (PMID 36131787, 2022). "Studies have also demonstrated that CTLA-4 is constitutively expressed on tumor cell lines at various degrees of intensity and can trigger apoptosis of CTLA-4-expressing tumor cells after interaction with soluble CD80 or CD86 recombinant ligands." (PMID 36104728, 2022).